IL22 (interleukin 22)
Diseases named in the same sentence as IL22 in open-access papers (continued):
Sharing a sentence is not in itself a finding about the gene and the disease.
systemic lupus erythematosus (31 papers, 2011 to 2025). An autoimmune multi-organ disease typically associated with vasculopathy and autoantibody production. "In the present study, we found indeed, in lupus-prone mice, IL-22 or IL-22R deficiency decreased production levels of serum ds-DNA autoantibodies and the levels of serum IgG, and increased the levels of serum C3." (PMID 33717066, 2021). "These outcomes indicate that IL-22 or IL-22R deficiency reduced macrophages infiltration in lupus-prone mice." (PMID 33717066, 2021). "Additionally, IL-22 exerts pathogenic effects in certain renal diseases, including systemic lupus erythematosus, IgA nephropathy, and anemia induced by CKD, due to recruitment of chemokines and uncontrolled activation of complement." (PMID 35432360, 2022). "Indeed, in lupus-prone mice, IL-22 or IL-22R deficiency decreased production of ds-DNA autoantibodies and the levels of serum IgG, and increased the levels of serum C3." (PMID 33717066, 2021). "Th17-lymphocytes are highly efficient producers of IL-21, IL-22, and especially IL-27; cytokines widely associated with the development of pathologies such as Systemic Lupus Erythematosus (SLE), RA, and Multiple Sclerosis (MS)." (PMID 32384594, 2020). "Pristane-induced lupus mice showed significantly higher serum levels of IL-1β, IL-2, IL-4, IL-13, IL-21, and IL-22 compared to those in WT mice." (PMID 35911685, 2022). "GDF-15 treatment significantly reduced levels of IL-1β, IL-2, IL-4, IL-21, and IL-22, by which treatment of lupus mice with 100 μg/kg GDF-15 had the most efficiency." (PMID 35911685, 2022). "Percentages of CD8+, CD11b+, CD19+, CD11C+ cells, TH2 cells, and pro-inflammatory cytokines (IL-1β, IL-2, IL-4, IL-21, and IL-22) were reduced after GDF-15 treatment in lupus mice." (PMID 35911685, 2022). "Studies related with Th22 cells and IL-22 in lupus patients are quite controversial, possibly due to small sample sizes." (PMID 35911703, 2022). "In our study, we found that IL-22 was mainly secreted by ILC3 in MRL/lpr mice, and deleting IL-22 or IL-22R decreased the systemic illness and lupus nephritis severity in lupus-prone mice." (PMID 33717066, 2021). "By immunoblotting, we detected the signaling pathway activated by IL-22/IL-22R in kidney epithelial cells of lupus-prone Mice." (PMID 33717066, 2021). "Polymorphisms in the IL-22 gene are associated with several diseases such as ulcerative colitis (UC), psoriasis vulgaris, bladder cancer, and systemic lupus erythematosus (SLE)." (PMID 32148440, 2020). "The effects of immunosuppressant drugs like prednisone, one of the most prescribed therapies to treat FS, were shown to be involved in the reduction of IL-22 in patients with systemic lupus erythematosus." (PMID 28855908, 2017). "The main cellular participation in both lupus groups was IL-17- and IL-22-producing cell responses both at skin and at peripheral blood but prevailed in DLE." (PMID 27041826, 2016). "Previous studies have shown decreased serum and plasma levels of IL-22 in patients with sarcoidosis and systemic lupus erythematosus." (PMID 22312190, 2012). "Moreover, administering GDF-15 to lupus-prone mice led to a decrease in several proinflammatory cytokines, including IL-1β, IL-18, and IL-22, highlighting its role in modulating the immune response." (PMID 40722837, 2025). "Moreover, increased expression of IL-2, IL-21, and IL-22 in lupus mice was downregulated by GDF-15 treatment." (PMID 35911685, 2022). "Increased IL-22 expression levels in female mice may potentially be due to a generally amplified female inflammatory response, as previously observed in murine lupus." (PMID 34638962, 2021). "Moreover, activated B cell infusion relieved lupus injuries via IL-22 production in vivo." (PMID 32127533, 2020). "We also found that deleting IL-22 or IL-22R downregulated CCL2 and CXCL10 expression, and decreased the filtration of macrophage into the kidney of lupus-prone mice." (PMID 33717066, 2021).
systemic lupus erythematosus (continued). "In our present study, based on mice models, we found that GDF-15 alleviated lupus by reducing renal damage, reversing CD8+, CD19+, and TH2 cells dysregulation, inhibiting production of IL-1β, IL-2, IL-4, IL-21, IL-22, ANA, and total IgG." (PMID 35911685, 2022). "By RNA-Seq, we found that gene expression of local chemokines in the kidney of lupus-prone mice was altered, and qRT-PCR further confirmed down-regulated expression of CXCL1, CCL2, and CXCL10 in the kidney of IL-22 or IL-22R KO MRL/lpr mice compared with MRL/lpr mice." (PMID 33717066, 2021). "The findings pointed to the fact that in the absence of IL-22 or IL-22R, lupus-prone mice do not exhibit some of the readily recognizable features of immune dysregulation characteristic of lupus." (PMID 33717066, 2021).
Hepatic steatosis (30 papers, 2012 to 2025). Steatosis is a term used to denote lipid accumulation within hepatocytes. "Another study reported that elevated levels of IL-22-producing ILC3s in the liver of HFD-induced MASH model were associated with reduced hepatic steatosis, while genetic deficiency of ILC3s worsened liver inflammation and fibrosis progression." (PMID 39156888, 2024). "Multiple preclinical studies show that recombinant IL-22 or IL-22Fc can reduce hepatic steatosis, fibrosis, and inflammation, and attenuate weight gain in diet-induced obese mice." (PMID 40243151, 2025). "IL-22-bispecific biologics targeting the liver and pancreas can reduce hepatic steatosis, inflammation, and fibrosis, and restore glycemic control in MASH mice." (PMID 40243151, 2025). "Our earlier work further demonstrated that WMT promotes the hepatic homing of ILC3s and alleviates liver lipid accumulation in patients with fatty liver disease via IL-22–mediated mechanisms." (PMID 41415268, 2025). "We observed a significant reduction in hepatic steatosis with IL-22-ScFv across multiple in-vivo models and a marked decrease in lipid-containing HEPG2 cells." (PMID 38811532, 2024). "These hepatic ILC3s demonstrate a mitigating effect on hepatic steatosis through the release of IL-22." (PMID 38940400, 2024). "It is possible that IL-22 contributes to the reduction of hepatic steatosis by impacting metabolism systemically at extraintestinal sites (eg, the liver)." (PMID 39761015, 2024). "Systemic treatment with IL-22 can ameliorate hepatic steatosis in preclinical models of MASLD and can reduce serum levels of triglycerides in human subjects." (PMID 39761015, 2024). "Targeted deletion of VIP receptor 2 in ILC3 resulted in higher production of IL-22 in ILC3 and was associated with a significant reduction in liver steatosis in mice under HFD." (PMID 39761015, 2024). "The direct hepatoprotective effects of IL-22 have been investigated in multiple models of liver injuries, including T cell-mediated hepatitis, acetaminophen-induced liver injury, fatty liver disease, and AH." (PMID 37908362, 2023). "Blocking the IAA–AhR–IL-22 axis by treatment with neutralizing anti-IL-22 antibodies abrogates the protective effects of IDO1 deficiency against insulin sensitivity, liver steatosis, and intestinal permeability." (PMID 36144238, 2022). "For example, IL-22 influences lipid metabolism in the liver, reduces lipogenesis and ameliorates hepatic steatosis induced by high fat diet." (PMID 30639417, 2019). "IL-22 has a protective role in HFD-induced hepatic steatosis by regulating lipid metabolism in the liver." (PMID 28969688, 2017). "In a chronic-binge ethanol feeding mouse model of alcohol induced liver injury the recombinant IL-22 treatment of the animals ameliorated liver injury and alcoholic fatty liver through the activation of STAT3 signaling pathway." (PMID 26199463, 2015). "Long-term administration of recombinant IL-22 to mice with a high fat diet induced hepatic steatosis and diminished the TNF-α level of the liver." (PMID 26199463, 2015). "Previous studies have revealed that IL-22 ameliorates fatty liver disease by downregulating hepatic expression of several lipogenic genes." (PMID 26064446, 2015). "IL-22 was found to enhance liver regeneration and protect the liver against fatty liver disease, as well as against ethanol-, concanavalin A-, carbon tetrachloride-, and Fas ligand-induced liver injury." (PMID 24799907, 2014). "In those models, IL-22 attenuated liver injury, prevented hepatic failure and improved hepatic steatosis." (PMID 22967278, 2012). "In metabolic disorders, the gut microbiota’s capacity to produce indoles is often diminished, resulting in reduced levels of protective molecules, such as GLP-1 and Interleukin-22 (IL-22), and subsequently increased intestinal permeability and hepatic steatosis." (PMID 41488302, 2025).
Hepatic steatosis (continued). "In addition, orally delivered recombinant IL-22 by an engineered probiotic strain (i.e., Lactobacillus reuteri) was biologically active and resulted in reduced weight gain, and hepatic steatosis in mice fed a high-fat, high-sucrose diet." (PMID 40794228, 2025). "These ILC3s demonstrated a mitigating effect on hepatic steatosis via the secretion of IL-22." (PMID 38940400, 2024). "Consequently, hepatic ILC3s alleviated hepatic steatosis and liver damage via the secretion of IL-22." (PMID 38940400, 2024). "Given the described hepatoprotective role of IL-22, we hypothesize that modulation of this neuroimmune circuit could potentially be an innovative approach for the control of liver steatosis." (PMID 39761015, 2024). "We next evaluated whether VIP-mediated inhibition of IL-22 production by intestinal ILC3 contributes to the liver steatosis phenotype in mice fed HFD." (PMID 39761015, 2024). "The effects of IL-22 in modulating metabolism were initially identified in hepatic steatosis." (PMID 37525285, 2023). "This study indicates that ILC3s can protect mice from liver steatosis through producing IL-22." (PMID 35574038, 2022). "Furthermore, treatment with IL-22 activates hepatic signal transducer and activator of transcription 3 (STAT3), ameliorates hepatic oxidative stress and alcoholic fatty liver, effectively alleviate the liver damage caused by alcohol and toxicant." (PMID 32760208, 2020). "Furthermore, liver-targeted delivery of IL-22 alleviated hepatic steatosis in HFD-fed NAFLD mice." (PMID 40794228, 2025). "Besides, IL-22 can regulate lipogenesis related genes and prevent liver steatosis." (PMID 35574038, 2022). "Recombinant IL-22 inhibited the hepatic expression of several lipogenic genes, including that of fatty acid synthase (FAS) in HepG2 cell line and HFD-induced NAFLD mice, which led to the reduction of hepatic steatosis." (PMID 40794228, 2025). "Moreover, intestinal IL-22 impacting intestinal barrier function, altering the host gut microbiota, and regulating the host expression of fat metabolism genes are additional hypotheses that could explain the observed protection in liver steatosis in Vipr2ΔILC3 mice." (PMID 39761015, 2024). "Since we observed an increase in IL-22 production by intestinal ILC3 in Vipr2ΔILC3 mice fed an HFD, we then asked whether these mice are protected from the development of hepatic steatosis." (PMID 39761015, 2024). "Moreover, hepatic ILC3s attenuated hepatic steatosis in both MAFLD patients and mice by secreting IL-22." (PMID 38940400, 2024). "In addition, IL-22 was shown to inhibit several hepatic lipogenic genes (e.g., fatty acid synthase (FAS)), thereby reducing liver steatosis as well." (PMID 39156888, 2024). "For example, interleukin-22 (IL-22), a member of the IL-20 subfamily, controls lipid metabolism in the liver via activation of the STAT3 signaling pathway and, consequently, reduces fatty liver disease." (PMID 32581074, 2020). "Therefore, IL-22 has great potential to serve as a therapeutic protein to reduce alcohol- and non-alcohol-induced fatty liver diseases." (PMID 32581074, 2020). "Taken together, these findings support the hypothesis that the increase of IL-22 production, potentially by intestinal ILC3, and the subsequent tissue response within the intestinal environment might be involved with the attenuation of hepatic steatosis that we observed in our study." (PMID 39761015, 2024).
multiple sclerosis (30 papers, 2011 to 2025). A progressive autoimmune disorder affecting the central nervous system resulting in demyelination. "Bacterial species that were more abundant in cases with disease-active treatment-naïve multiple sclerosis were positively linked to a group of plasma cytokines including IL-22, IL-17A, IFN-β, IL-33, and TNF-α." (PMID 36604748, 2023). "IL-22 has been linked to a number of chronic autoimmune and inflammatory illnesses, including multiple sclerosis (MS) and psoriasis." (PMID 36176437, 2022). "In conclusion, our findings constitute the first step towards delineating the therapeutic potential of IL-22 in the management of patients with multiple sclerosis (MS)." (PMID 39040539, 2024). "It is also been observed that Th‐17 cells migrate more effectively to the central nervous system (CNS) parenchyma in autoimmune disorders such as multiple sclerosis, due to their secretion of IL‐17 and IL‐22 which can disrupt the tight junctions of the BBB." (PMID 37165998, 2023). "IL-22 receptor was detected in human astrocytes of both healthy controls and multiple sclerosis patients, and IL-22 treatment reduced TNF-α-induced apoptosis of astrocytes." (PMID 32843067, 2020). "IL-22 contributes to pathogenesis of psoriasis by inducing the proinflammatory S100 family of calcium binding proteins and plays a role in multiple sclerosis by promoting leukocyte infiltration into the brain." (PMID 22952908, 2012). "Previous studies have shown that both IL-17 and IL-22 contribute to multiple sclerosis lesions by promoting transmigration of Th17 lymphocytes across the blood brain barrier." (PMID 22952908, 2012). "This may stimulate a defensive pathway When released from Th17 ​cells in the periphery, Il-22 may drive immunopathogenesis in multiple sclerosis, and may mediate anti-inflammatory activity in astrocytes through a similar pathway." (PMID 34589808, 2021). "Th22 cells and IL-22 are increased in patients with multiple sclerosis." (PMID 28751644, 2017). "Notably, type I IFN, namely IFN-β, has previously been reported to inhibit spontaneous release of IL-22 from otherwise unstimulated CD4+ T cells obtained from multiple sclerosis patients." (PMID 26152778, 2015). "On the other hand, pro-inflammatory cytokines such as IL-6, IL-1β, IL-17, IL-22, TNF-α, IL-12, and IFN-γ are thought to play a pivotal role in the pathogenesis of multiple sclerosis (MS) through various signaling pathways." (PMID 40507498, 2025).
diabetes (28 papers, 2011 to 2025). "Interleukin (IL)-21 and IL-22 have been implicated in the pathogenesis of type 1 diabetes mellitus (T1DM)." (PMID 40422866, 2025). "Our data are novel because previous studies on IL-22 and metabolic disorders mainly focused on mouse models, whereas research in humans is warranted to assess the potential role of IL-22 as biomarker for diabetes risk or as candidate for treatment studies." (PMID 28143481, 2017). "In any case, our data consistently argue against the initially hypothesised inverse association between physiological serum levels of IL-22 and diabetes risk." (PMID 28143481, 2017). "We aimed to identify correlates of serum IL-22 levels and to test the hypothesis that higher IL-22 levels are associated with lower diabetes incidence." (PMID 28143481, 2017). "Diabetes progression in the diabetes-prone NOD mice is associated with reduced gut mucosal integrity, impairing the protective IL-17 and IL-22 responses of gut-resident MAIT cells and exacerbating systemic inflammation." (PMID 40607421, 2025). "Our data indicate that diabetes leads to a predominantly Th17-type immune response profile in the colon, due to increased levels of IL-17, IL-22, and TNF-α." (PMID 40496562, 2025). "Diabetes increased IL-10, IL-17, IL-22, and TNF-α levels, and reduced IL-1β levels in the colon of diabetic mice compared to non-diabetic controls, without altering the content of IL-4, IL-6, and TGF- β1." (PMID 40496562, 2025). "For example, Roseburia intestinalis promotes the production of IL-22 an anti-inflammatory cytokine, while attenuating insulin resistance and the development of diabetes." (PMID 39070791, 2024). "Correlations were observed between CPI and peripheral concentrations of both PGE2 and HbA1c; a significant correlation was also observed between IL-22 and duration of diabetes." (PMID 33234730, 2020). "Serum IL-22 levels are significantly reduced in TB patients with T2DM compared with TB patients without T2DM, however limited information is available regarding the role of IL-22 during TB-diabetes comorbidity." (PMID 31809521, 2019). "Previous studies demonstrated that deletion of IL-22 suppressed diabetes progression led by autoreactive T cells, and that rmIL-22 treatment did not block streptozotocin-induced type 1 diabetes." (PMID 28779211, 2017). "Our study suggests that, at this dosing regimen introduced either prior to overt diabetes or at diagnosis of diabetes, recombinant mouse IL-22 therapy cannot prevent autoimmune diabetes, or prolong the honeymoon period in the NOD mouse." (PMID 28779211, 2017). "IL-22 suppressed diabetes-induced glomerular and interstitial fibrosis as indicated by reduced fibronectin, collagen IV, vimentin and α-SMA expression in kidney tissue lysates." (PMID 28726774, 2017). "This explanation suggests similarities between IL-22 and IL-1RA, which also has diabetes- and atheroprotective effects, but higher circulating levels indicate a higher risk of type 2 diabetes and cardiovascular disease." (PMID 28143481, 2017). "At this time, NOD mice in the control arm were treated with LinBit insulin pellets and randomised to bi-weekly therapeutic injections of either PBS or IL-22 (200 ng/g) and followed until overt diabetes was diagnosed, as defined above." (PMID 28779211, 2017). "The beneficial effect of IL-22 reported here is consistent with some previous findings regarding its role in diabetes and atherosclerosis." (PMID 27829708, 2016). "Concentrations of IL-22 in culture supernatants of unstimulated or activated PBMCs from type 2 diabetes mellitus and healthy controls." (PMID 22312190, 2012). "Another interesting finding in this study was that IL-22 exhibited a positive correlation with the duration of diabetes." (PMID 22312190, 2012).